GAS5 (growth arrest specific 5)
Diseases named in the same sentence as GAS5 in open-access papers (continued):
Sharing a sentence is not in itself a finding about the gene and the disease.
atherosclerosis (continued). "Our earlier work showed that expression of long noncoding RNA-growth arrest-specific 5 (lncRNA GAS5) was significantly increased in the plaque of atherosclerosis collected from patients and animal models." (PMID 28945793, 2017). "This high-specific expression in lesion sites suggests that GAS5 may play a crucial role in the development and progression of atherosclerosis." (PMID 40563948, 2025). "Because GAS5 can directly suppress miR-221, the lncRNA GAS5/miR-221/Sirt1 axis may modulate endothelial function during atherosclerosis." (PMID 40563948, 2025). "This table clearly demonstrates that GAS5 regulates different biological processes through distinct molecular mechanisms in various cells, ultimately exerting complex effects on the development of atherosclerosis." (PMID 40563948, 2025). "By targeting miR-135a, GAS5 can impact the progression of atherosclerosis (AS)." (PMID 39941145, 2025). "The lncRNA GAS5 (growth-arrest-specific 5) is crucial for the development of atherosclerosis." (PMID 40941416, 2025). "To illustrate, elevated concentrations of GAS5 are detected in rat models of atherosclerosis." (PMID 40563948, 2025). "The main goal of this review is to summarize the current understanding of GAS5’s complex role in blood vessels during atherosclerosis, which could highlight new paths for treatment." (PMID 40563948, 2025). "The authors showed that the expression of GAS5 was elevated in rats with atherosclerosis." (PMID 39272765, 2024). "In a recent study of atherosclerosis, EVs isolated from monocytes were found to contain the long non-coding RNA (lncRNA) GAS5 which may be able to accelerate progression of atherosclerosis by enhancing the apoptosis of vascular endothelial cells." (PMID 36891265, 2023). "LncRNA GAS5 regulates apoptosis of macrophages and vascular endothelial cells in atherosclerosis." (PMID 35044621, 2022). "With regard to lncRNA-modulated EC autophagy in atherosclerosis, it is reported that GAS5 knockdown reduces cell apoptosis in human aortic ECs in response to oxLDL, decreases SQSTM1/p62 levels, and increases LC3-II/I ratio, and these effects are reversed by suppressing miR-26a expression." (PMID 36082127, 2022). "Moreover, the study has shown that exogenous lncRNA GAS5 regulates macrophage apoptosis in atherosclerosis." (PMID 35573783, 2022). "GAS5 was significantly increased in atherosclerosis patients' plaque than in normal people." (PMID 34179148, 2021). "Myr possessed an anti-inflammatory and anti-EndMT function against ox-LDL-induced HUVEC injury by regulating the GAS5/miR-29a-3p, indicating that Myr may have an important therapeutic function for atherosclerosis." (PMID 34608195, 2021). "In addition, knockdown of GAS5 has the potential to prevent the progression of atherosclerosis by reducing enhancer of zeste homolog 2 (EZH2)-mediated ATP-binding cassette transporters A1 (ABCA1) transcription." (PMID 34781960, 2021). "GAS5 is not only related to diabetes but may also be an effective target for atherosclerosis treatment." (PMID 35011565, 2021). "GAS5 overexpression in apoE−/− mice with atherosclerosis also increased total cholesterol (TC), free cholesterol (FC), cholesterol ester (CE), low-density lipoprotein (LDL) levels, aortic plaque, and lipid accumulation; however, silencing of GAS5 prevented the progression of atherosclerosis." (PMID 34179148, 2021). "Previous studies have shown that GAS5 silencing repressed atherosclerosis's malignant progression." (PMID 34179148, 2021). "Overexpression of GAS5 in macrophage-derived foam cells increased the intracellular lipid accumulation, whereas the inhibition of this lncRNA expression inhibited intracellular lipid accumulation and its progression atherosclerosis." (PMID 33478141, 2021).
atherosclerosis (continued). "MiR-26a could attenuate hyperlipidemia and the inflammatory response in high fat-fed ApoE−/− mice, indicating that GAS5 might affect the development of atherosclerosis via regulation of cholesterol efflux and inflammation." (PMID 32082313, 2020). "The onset of atherosclerosis is partly mediated by EC dysfunction, when subjected to various noxious stimuli For example, lncRNA GAS5 is highly expressed in ECs, and downregulation of lncRNA GAS5 exacerbates hypertension-induced microvascular dysfunction." (PMID 32082313, 2020). "These evidences suggest that GAS5 might promote the development of atherosclerosis via regulation of EC function, cholesterol efflux, inflammation, and might be used as a therapeutic target." (PMID 32082313, 2020). "Interestingly, these effects of GAS5 on EC apoptosis is mediated by macrophage derived exomes after oxLDL stimulation, which demonstrated the interplay of macrophage and EC during atherosclerosis development." (PMID 32241300, 2020). "LncRNA GAS5 is involved in several biologic processes, including glucocorticoid (GC) actions, inflammatory and autoimmune diseases, vascular endothelial cells apoptosis and atherosclerosis, FGSC proliferation." (PMID 30612561, 2019). "In addition, recent evidence pointed to lncRNA GAS5 a role in atherosclerosis and autoimmune diseases, which are widely recognized as KS comorbidities." (PMID 30612561, 2019). "As membrane vesicles, exosomes are crucial in the intercellular communications and may be a key mediator of lncRNA GAS5, which provide the possibility of an alternative strategy for treatment of atherosclerosis." (PMID 28945793, 2017). "Whether macrophage derived exosomal lncRNA GAS5 modulate the function of endothelial cells in atherosclerosis is also investigated." (PMID 28945793, 2017). "LncRNAs GAS5, ranked fourth in atherosclerosis, is significantly increased in the plaques of atherosclerosis patients compared with normal subjects and may lead to new clinical applications." (PMID 28051121, 2017). "In essence, lncRNA GAS5 is a crucial determinant in maintaining endothelial cell homeostasis by modulating numerous cellular mechanisms, including proliferation, apoptosis, autophagy, and inflammatory responses, all of which are vital for the development and progression of atherosclerosis." (PMID 40563948, 2025). "Therefore, it appears that targeting GAS5 could be a promising strategy for atherosclerosis therapy." (PMID 39273193, 2024). "Therefore, due to the potential involvement in the pathogenesis of atherosclerosis, GAS5 could be a promising target in the diagnosis and therapy of this arterial condition." (PMID 39272765, 2024). "Likewise, exosomes can also be loaded with lncrnas, one article explores the regulation of exosomal lncRNA GAS5 on apoptosis of macrophages and vascular endothelial cells in atherosclerosis, which revealed that gas5 has potential therapeutic implications in the prevention of atherosclerosis." (PMID 37823027, 2023). "As a consequence, inhibition of GAS5 may be a useful strategy to treat atherosclerosis." (PMID 36082127, 2022). "Given that lncRNA seems to be involved in various biologic processes, such as GC actions, inflammatory and autoimmune diseases, apoptosis and atherosclerosis, we speculate that lncRNA GAS5 decreased expression may be involved in the some typical phenotypes of DS patients." (PMID 32624686, 2020). "Therefore, lncRNA GAS5 has been suggested as a target for the therapy of atherosclerosis." (PMID 30612561, 2019). "Deregulation of lncRNAs, including H19, TUG1, GAS5, RAPIA, MIAT, CASC11, NEXN-AS1, and lnc00113, has been observed in individuals with atherosclerosis." (PMID 40941416, 2025). "Overexpression of GAS5 increased levels of TC, LDL, cholesterol ester (CE), and free cholesterol (FC) in ApoE−/− mice with atherosclerosis." (PMID 40941416, 2025). "Consequently, GAS5 could emerge as a promising focus for developing atherosclerosis treatments." (PMID 40563948, 2025).
atherosclerosis (continued). "The deregulation of many lncRNAs, including RAPIA, H19, CASC11, GAS5, TUG1, MIAT, lnc00113, and NEXN-AS1, has been observed in patients with atherosclerosis." (PMID 39273193, 2024). "GAS5 knockdown is considered to promote RCT and inhibit the accumulation of intracellular lipids, preventing atherosclerosis progression." (PMID 34940525, 2021). "Thus, targeting GAS5 might be a promising way for atherosclerosis therapy." (PMID 34179148, 2021). "GAS5 binds to EZH2 and then inhibits the expression of ABCA1, thus accelerating the progression of atherosclerosis." (PMID 34781960, 2021). "Such lncRNAs with relevance to atherosclerosis include ANRIL, lincRNA‐p21, MALAT1, MEG3, TUG1, GAS5 and MANTIS." (PMID 33340430, 2021). "GAS5 has different splicing isoforms (such as GAS5a, GAS5b), but their specific functions and regulatory mechanisms in atherosclerosis have not been sufficiently studied." (PMID 40563948, 2025). "Moreover, GAS5 sponges miR-221, leading to the increased production of pro-inflammatory cytokines and MMP-2/9 expression in atherosclerosis." (PMID 36671717, 2022). "Together, circRNA circDENND1B and the considered above lncRNA MALAT1, CHROME, GAS5, MEG3 function as ceRNAs and bind miRNAs that suppress the expression of ABCA1, which increases the level of ABCA1 mRNA and prevents the development of atherosclerosis." (PMID 34940525, 2021). "Indeed, GAS5 suppression stimulates RCT, suppresses intracellular lipid accumulation, and, as a result, decreases the progression of atherosclerosis." (PMID 34940525, 2021). "Moreover, exosomes derived from lncRNA GAS5-overexpressing THP-1 cells enhanced the apoptosis of vascular endothelial cells, suggesting exosomal lncRNA GAS5 participated in the process of atherosclerosis." (PMID 33192490, 2020).
ovarian carcinoma (47 papers, 2017 to 2025). A malignant neoplasm originating from the surface ovarian epithelium. "GAS5 downregulation causes ovarian cancer cells to proliferate more quickly, experience a lower rate of apoptosis, and grow larger tumors in rats." (PMID 39337410, 2024). "They found an extremely low expression of lncRNA GAS5 in epithelial ovarian cancer (EOC) samples, which was associated with prognosis." (PMID 39337410, 2024). "The downregulation of miR-21 and upregulation of SPRY2 are observed in conjunction with a considerable inhibition of ovarian cancer cell growth caused by GAS5 overexpression." (PMID 39337410, 2024). "The expression of GAS5 is low in ovarian cancer and is associated with the low survival of ovarian cancer patients according to public ovarian cancer databases." (PMID 37639158, 2023). "GAS5 expression levels were downregulated in tissues and cell lines of ovarian cancer and associated with advanced clinical stage." (PMID 34204094, 2021). "Growth arrest-specific 5 is downregulated in ovarian cancer, with this low expression associated with shorter disease-free period and lower overall survival rate of ovarian cancer patients." (PMID 33996797, 2021). "Although ovarian cancer is very common in women, there is only one report investigating the association between miRNAs and GAS5 in it." (PMID 33076450, 2020). "Low expression of lncRNA GAS5 was associated with poor prognosis in patients with ovarian cancer." (PMID 36105363, 2022). "Moreover, a report showed that lncRNA GAS5 was associated with ovarian cancer progression by regulating histone H3 at lysine 27 (H3K27me3)." (PMID 35360864, 2022). "A better understanding of the mechanism of GAS5 in the evolution and progression of human ovarian cancer may lead to new diagnostic and therapeutic approaches for ovarian cancer." (PMID 29229673, 2018). "To investigate the effect of GAS5 on the malignant behavior of these ovarian cancer cells, we tried to define whether loss of GAS5 expression contributed to the ovarian cancer progression." (PMID 29229673, 2018). "However, the underlying mechanism of lncRNA GAS5 in regulating the target expression in ovarian cancer cells needs further study." (PMID 29229673, 2018). "Our findings showed that loss of lncRNA GAS5 in ovarian cancer cells may contribute to the tumor progression and could be a potential therapeutic target for diagnosis and therapy for clinical application." (PMID 29229673, 2018). "In addition, the role of lncRNA GAS5 in ovarian cancer was associated with inflammasome formation and pyroptosis." (PMID 29229673, 2018). "The luciferase experiment revealed that, in ovarian cancer-derived A2780 cells, miR-21 was directly targeted by GAS5, and that its target gene was SPRY2." (PMID 39337410, 2024). "In ovarian cancer, a higher tumor volume and an FIGO stage (III–IV) are associated with low GAS5 expression and high miR-196a-5p expression." (PMID 39337410, 2024). "By decreasing the expression of miR-96-5p, GAS5 overexpression can drastically impair the ability of ovarian cancer cells to proliferate and invade." (PMID 39337410, 2024). "Treatment with lncRNA H19, MAFG-AS1 or GAS5 is a promising treatment for ovarian cancer, although further research is needed in this area." (PMID 39337410, 2024). "GAS5 influences ovarian cancer cell proliferation by regulating the expression of cyclin D1, p21, and apoptosis protease-activating factor 1 (APAF1)." (PMID 39337410, 2024). "The research verified that overexpression of GAS5 inhibited the PI3K/AKT/mTOR signaling pathway in ovarian cancer cells." (PMID 37639158, 2023). "For instance, a report suggested that lncRNA GAS5 is a tumor suppressor in ovarian cancer, with decreased expression in cancer cells." (PMID 37720188, 2023). "In terms of mechanism, the research results showed that GAS5 affected the protein stability of hnRNPK, and then affected the occurrence and development of ovarian cancer." (PMID 37639158, 2023).
ovarian carcinoma (continued). "The suppressive effect of GAS5 on migration and invasion in ovarian cancer cells was reversed by overexpression of hnRNPK by transwell assays." (PMID 37639158, 2023). "To explore the functions of GAS5 in ovarian cancer, we characterized the cellular phenotypes of ovarian cancer cells with overexpression of GAS5." (PMID 37639158, 2023). "We investigated the effects of overexpressing GAS5 on the growth and metastasis of ovarian cancer cell lines including OVCAR3 and A2780." (PMID 37639158, 2023). "GAS5 overexpression inhibited the growth of ovarian cancer cell lines as determined by (Cell Counting Kit-8) CCK-8 and colony formation assays." (PMID 37639158, 2023). "Overexpression of GAS5 increased the death rate of ovarian cancer cells by comparing early apoptosis (Q1-LR) values using flow cytometry." (PMID 37639158, 2023). "When ovarian cancer cells were transfected with the GAS5 plasmids, Western blotting verified that hnRNPK protein was downregulated and the RNA expression of hnRNPK was no significant change by RT-qPCR." (PMID 37639158, 2023). "Our study enriches the molecular mechanism of GAS5 and regulates ovarian cancer progression via hnRNPK, which provided a novel therapeutic strategy to treat ovarian cancer." (PMID 37639158, 2023). "Our study showed one of the mechanisms that GAS5 inhibited ovarian cancer metastasis by down-regulating hnRNPK expression, and GAS5 can be used to predict the prognosis of ovarian cancer patients." (PMID 37639158, 2023). "To reveal the regulatory mechanism of GAS5 in ovarian cancer, we used RNA pull-down and mass spectrometry analysis to screen the proteins co-interacting with GAS5." (PMID 37639158, 2023). "In summary, the finding of this study illustrates the vital function of GAS5-mediated hnRNPK protein stability in ovarian cancer." (PMID 37639158, 2023). "Our research provided new insights into the mechanism by which GAS5 inhibited the progression of ovarian cancer." (PMID 37639158, 2023). "Transwell assays demonstrated that overexpressing GAS5 inhibited the migration and invasion of ovarian cancer cells." (PMID 37639158, 2023). "Previous studies found that both UCA1 and GAS5 lncRNAs play roles in the development of ovarian cancer." (PMID 35901079, 2022). "Increased expression of lncRNA GAS5 led to G0/G1 phase arrest and triggered apoptosis in ovarian cancer cells." (PMID 36105363, 2022). "Using microarray and RT-PCR analysis, one group found that lncRNA GAS5 was dramatically downregulated in ovarian cancer specimens." (PMID 36105363, 2022). "In ovarian cancer, long noncoding RNA growth arrest-specific transcript 5 (lncRNA GAS5) functions as a suppressor of tumor progression by inducing inflammasome formation." (PMID 36059539, 2022). "In ovarian cancer, growth arrest-specific transcript 5 (GAS5) can hinder the growth of cancer cells through proptosis mediated by caspase-1." (PMID 35562678, 2022). "It is reported that LncRNA GAS5 induces the occurrence of ovarian cancer via inflammasome formation during pyroptosis process." (PMID 35237509, 2022). "In line with the role of GAS5, cisplatin-resistant ovarian cancer cells displayed lower expression of lncRNA GAS5." (PMID 36105363, 2022). "In particular, in ovarian cancer it has been shown that repression of GAS5 promotes cell proliferation, migration, and invasion and correlates with poor prognosis in patients." (PMID 34204094, 2021). "Overexpression of GAS5 inhibited the proliferation of ovarian cancer cells, resulting in decreased expression of miR-21 and increased SPRY2." (PMID 34204094, 2021). "In epithelial ovarian cancer, GAS5 interacts with E2F4 (E2F Transcription Factor 4), recruiting E2F4 to the PARP1 promoter." (PMID 34202777, 2021). "GAS5 overexpression promotes apoptosis of ovarian cancer cells such as A2780, HEY, OVCAR3, and SKOV3, and increases the sensitivity of HEY and SKOV3 cells to the anticancer agent cisplatin." (PMID 33996797, 2021).